BTRC (beta-transducin repeat containing E3 ubiquitin protein ligase)
Diseases named in the same sentence as BTRC in open-access papers (continued):
Sharing a sentence is not in itself a finding about the gene and the disease.
osteosarcoma (4 papers, 2014 to 2025). A usually aggressive malignant bone-forming mesenchymal neoplasm, predominantly affecting adolescents and young adults. "The findings will give insight into functional interactions between lnc-SELPLG-2:1 and hsa-miR-10a-5p, hsa-miR-10a-5p, and BTRC, which are involved in osteosarcoma." (PMID 36199080, 2022). "As mentioned in a previous study, BTRC showed significantly downregulated expression in osteosarcoma." (PMID 36199080, 2022). "Lnc-SELPLG-2:1 is an oncogenesis activator in osteosarcoma, and its functions are performed via hsa-miR-10a-5p /BTRC cascade." (PMID 36199080, 2022). "A response test was used to confirm the mechanism by which lnc-SELPLG-2:1 sponge hsa-miR-10a-5p promotes the expression of BTRC to regulate osteosarcoma." (PMID 36199080, 2022). "Several authors associated the pathways involving BTRC with osteosarcoma, but no studies described its involvement in STS." (PMID 40007535, 2025). "In addition, we demonstrated that lnc-SELPLG-2:1/hsa-miR-10a-5p/BTRC is a candidate regulation pathway for lncRNA in osteosarcoma." (PMID 36199080, 2022). "Therefore, we believe that lnc-SELPLG-2:1 regulates osteosarcoma by promoting the mRNA and protein expression of BTRC via the competitive binding of hsa-miR-10a-5p." (PMID 36199080, 2022). "Competitive binding of lnc-SELPLG-2:1 to hsa-hsa-miR-10a-5p prevented BTRC from miRNA-mediated degradation, thereby activating the expression of VIM, MMP9, and MMP2, promoting osteosarcoma cell proliferation, migration, and invasion, and inhibiting apoptosis." (PMID 36199080, 2022). "According to our findings, osteosarcoma specimens with upregulated lnc-SELPLG-2:1 and downregulated hsa-miR-10a-5p exhibited upregulated BTRC expression." (PMID 36199080, 2022).
adrenocortical carcinoma (2 papers, 2020 to 2024). "lncRNA-ASB16-AS1 promotes ubiquitin E3 ligase BTRC-mediated ubiquitination and degradation of LATS1 to inhibit adrenocortical carcinoma cell growth." (PMID 37897508, 2024). "The results turned out that knock-down of BTRC abolished the down-regulation of HuR, CDK6, and IGF1R expression upon enhanced expression of ASB16-AS1 in adrenocortical carcinoma cells." (PMID 33219221, 2020).
Hepatitis (2 papers, 2021 to 2024). Inflammation of the liver. "Apart from ATGL degradation, the continuously elevated BTRC levels in hepatic steatosis also promote liver inflammation." (PMID 37873692, 2024).
hepatoblastoma (2 papers, 2019 to 2023). Hepatoblastoma (HB) is a malignant hepatic tumor and is the most common pediatric liver cancer. "In addition, the upregulation of BTRC mRNA and the concordant accumulation of β-TrCP1 in the cytoplasm and nucleus are found in clinical samples of patients with hepatoblastoma and hepatoblastoma cell lines." (PMID 37686524, 2023).
ovarian carcinoma (2 papers, 2020 to 2024). A malignant neoplasm originating from the surface ovarian epithelium. "Also, it selectively reduces the levels of other cancer related IGFBP1 mRNA targets, including CDC34, BTRC, and COL5A, similar to the effect by knockdown of IGFBP1 in ovarian cancer cells." (PMID 32414222, 2020).
medulloblastoma (1 paper, 2023). A malignant, invasive embryonal neoplasm arising from the cerebellum. "BTRC (the gene encoding β-TrCP1) is located at human chromosome 10q24.3, which contains a gene that is mutated in prostate tumorigenesis and frequently deleted in medulloblastomas." (PMID 37686524, 2023).
ovarian tumors (1 paper, 2014). "To assess the possibility that alteration to these components may be contributing to NRF2 activation in ovarian tumors, we evaluated DNA-level alterations affecting the genes involved in this BTRC/SKP1/CUL1 complex." (PMID 25114896, 2014).
shigellosis (1 paper, 2017). Shigellosis is a bacterial infection leading to dysentery and is caused by Shigella, which are small, ubiquitous Gram-negative bacteria belonging to the enterobacteria family. "The protein encoded by BTRC is a member of the F-box protein family and disease associated with BTRC is Shigellosis." (PMID 28587194, 2017).
steatosis (1 paper, 2024). Increased lipid within the cytoplasm of cells. "Moreover, adenovirus-mediated knockdown of BTRC ameliorated steatosis in HFD-fed mouse livers and oleic acid-treated liver cells via upregulating the ATGL level." (PMID 37873692, 2024).
tumor (102 papers, 2004 to 2025). "Co-expressed genes and TIF miRNAs associated with tumor grade were BTRC, CHST1, miR-10a/b, miR-107, miR-301a, and miR-454." (PMID 32605588, 2020). "Collectively, these observations suggested that circRHCG contributed to tumor progression and M2 polarization through the BTRC/TFEB axis in vivo." (PMID 38287113, 2024). "Knockdown of circRHCG reduced tumor growth, metastasis, and M2 polarization through the BTRC/TFEB axis in vivo." (PMID 38287113, 2024). "CDK1 accumulation in patients’ tumors shows a negative correlation with beta-transducing repeat containing E3 ubiquitin protein ligase (BTRC) and exhibits a positive correlation with the degree of tumor malignancy." (PMID 37311884, 2023). "BTRC is proposed to play dual roles in cancers, displaying oncogenic properties in one context and tumor‐suppressive characteristics in another." (PMID 34197030, 2022). "Our results agree with these studies; we see a downregulation of BTRC in high-grade tumor tissues and an upregulation of miR-10a, miR-10b, and miR-107 in matched interstitial fluids of these tumors." (PMID 32605588, 2020). "On the other hand, the EBV-miR-BART10-3p mimics-enhanced tumor cell invasion and migration were rescued by overexpression of BTRC in either HNE2 or 5-8F cells." (PMID 26497204, 2015). "In addition, the mRNA levels of BTRC with 9N ins/del or 9N del/del were reduced in HCC tumor tissues compared to 9N ins/ins." (PMID 37686524, 2023). "BTRC is proposed to have tumor-suppressive functions, while miR-10b is oncogenic; as such, it should be of interest to study this pair in relation to tumor invasiveness and metastasis." (PMID 32605588, 2020). "For example, the βTrCP gene (BTRC) is somatically altered in various cancer types and the aberrant protein exhibits both oncogenic and tumor suppressive activities within cells." (PMID 34445249, 2021). "We generated and confirmed at genomic and mRNA levels the BTRC-MGMT and SAR1A-MGMT fusion events in the MGMT-negative patient-derived h543 GBM tumor spheres." (PMID 32753598, 2020). "BTRC has been proposed to be a DRG, having oncogenic properties in one context and anti-tumor functions in another." (PMID 32605588, 2020). "Previous studies have demonstrated that miR-BART1, miR-BART7-3p, miR-BART9 and miR-BART10-3p induce tumor metastasis by targeting PTEN, E-cadherin and BTRC, respectively." (PMID 30477559, 2018). "In this study, we first examined the expression of both EBV-miR-BART10-3p and BTRC mRNA in 28 NPC and 9 non-tumor nasopharyngeal epithelial biopsies by real-time PCR." (PMID 26497204, 2015). "In this study, we found high abundance of circRHCG in TNBC-derived exosomes, and exosomal circRHCG promoted M2 polarization via enhancing BTRC-dependent ubiquitination and degradation of TFEB, thus facilitating tumor cell metastasis and accelerating TNBC progression." (PMID 38287113, 2024). "We also observed a fold increase in the expression of DVL1 (and BTRC to a lesser extent) in TN tumor samples as compared to non-TN tumor samples." (PMID 24143235, 2013).
cancer (98 papers, 2010 to 2025). A tumor composed of atypical neoplastic, often pleomorphic cells that invade other tissues. "Just as for miR-107, the role of β-TrCP (encode by BTRC) in cancer development and progression is convoluted." (PMID 32605588, 2020). "BTRC is a gene that mediates IκBα ubiquitination and proteasomal degradation and is involved in diseases such as cancer." (PMID 41480590, 2025). "BTRC has also been demonstrated a vital role in the EMT process since BTRC mediates the snail's ubiquitination in cancer and the former's inhibition leads to the upregulation of snails, which induces EMT." (PMID 33628829, 2021). "Each of these genes has been verified possessing important functions in cancer, with BTRC being the most noteworthy." (PMID 33628829, 2021). "It is conceivable that WBP2 could be involved in the control of mRNA stability of oncogenes other than BTRC to drive cancer biology." (PMID 34197030, 2022). "The modulation of BTRC level and activity plays an important role in several cancers." (PMID 33628829, 2021). "In addition, cancer stemness is known to be suppressed by beta-transducin repeat containing E3 ubiquitin-protein ligase (BTRC, also known as β-TrCP), one of the SCF components." (PMID 33799952, 2021). "One of the F-box proteins, BTRC, also called β-TrCP, has been demonstrated to regulate cellular processes by recognizing numerous essential molecules, including IκBα and β-catenin, for degradation and play a significant role in cancer development and inflammation." (PMID 37873692, 2024). "Subsequently, we established a PPI network and corroborated that BTRC played a pivotal role in the PPI network and was closely related to cancer." (PMID 33628829, 2021). "Moreover, it also selectively reduces the levels of other cancer-related IGF2BP1 mRNA targets including CALM1, CDC34, COL5A, and BTRC, similar to the effect by RNAi knockdown of IGF2BP1 both in IGROV-1 and SK-MEL2 cancer cells." (PMID 29954406, 2018). "Several targets of miR-195 reported in other cancers, such as VEGF and BTRC, are not decreased by miR-195 in NSCLC, supporting the idea that the target space of a given miRNA is context-dependent." (PMID 29416000, 2018).
BTRC also shares sentences with these, for which no sentence is quoted: gastric cancer (17 papers); infection (13); renal fibrosis (7); glioblastoma (5); HIV-1 infection (5); triple-negative breast carcinoma (5); virus infection (5); colorectal tumors (3); leukemia (3); lung adenocarcinoma (3); multiple myeloma (3); colon adenocarcinoma (2); diabetic nephropathy (2); meningioma (2); renal carcinoma (2); sarcoma (2); acute liver inflammation (1); brain cancer (1); breast invasive carcinoma (1); breast tumors (1); Burkitt lymphoma (1); cardiac hypertrophy (1); cardiomyopathies (1); cervical cancer (1); cholangiocarcinoma (1); coronary artery disease (1); diabetes (1); Ectrodactyly (1); emphysema (1); endotoxemia (1).
A further 33 diseases each share a sentence with BTRC in 1 paper.